TGFBI (transforming growth factor beta induced)
Diseases named in the same sentence as TGFBI in open-access papers (continued):
Sharing a sentence is not in itself a finding about the gene and the disease.
tumor (continued). "We further explored the role of TGFBI in OSCC tumor growth and metastasis via TGFBI knockout in the HSC-3 cell line and a xenograft animal study." (PMID 31598162, 2019). "TGFBI was more prevalent in cancer than in benign epithelium and was found at lower levels in tumor stroma than in benign stroma." (PMID 29858602, 2018). "On the other hand, TGFBI has also been shown to act as a tumor promoter in the gastrointestinal tract, and its overexpression in mice increased the rate of formation of spontaneous gastrointestinal and N,N-diethylnitrosamine-induced liver tumors." (PMID 28106769, 2017). "This is supported by the work of others which suggests a correlation of SPARC and TGFBI expression with tumor metastasis." (PMID 27622658, 2016). "This has raised an intriguing possibility that the pro- and contra-tumor effects of TGFBI are tissue- and tumor type-dependent events." (PMID 25889002, 2015). "We tested serum TGFBI levels of some tumor patients before and after treatment (tumorectomy, chemotherapy or irradiation)." (PMID 25889002, 2015). "To address this question, we assessed spontaneous tumor incidence in aged (>16-month-old) Tg mice with β-actin promoter-driven over-expression of TGFBI." (PMID 25889002, 2015). "Quite a few correlative studies have revealed conflicting roles of TGFBI as either tumor suppressor or promoter." (PMID 25889002, 2015). "The list gives the general impression that TGFBI is a promoter of gastrointestinal tract cancers, and functions as a tumor suppressor of other cancers." (PMID 25889002, 2015). "Of note, overexpression of TGFBI and interferon-induced proteins IFIT2, IFIH1 and IFI44L in the residual tumor were also associated with reduced RFS." (PMID 26021444, 2015). "To corroborate observations based on spontaneous tumor incidence in aged mice, we tested the effect of TGFBI overexpression and KO in mice exposed to DEN." (PMID 25889002, 2015). "Aged TGFBI gene knockout (KO) mice manifest increased tumor risks (37% versus 8.3% in wild type (WT)) mice at 13–20.5 months of age." (PMID 25889002, 2015). "In P regions showing clear evidence of tumor cell infiltration, TGFBI staining was found extracellularly and in the basement membrane of vessels, reflecting the staining observed in C samples (not shown)." (PMID 26188123, 2015). "In a study with TGFBI null mice, loss of TGFBI promoted cell proliferation via aberrant activation of the CREB-cyclin D1 pathway and predisposed mice to spontaneous tumor development." (PMID 25369402, 2014). "Microarray analysis of tumor cells demonstrated upregulation of TGFBI expression upon DDR1 knockdown, which was subsequently confirmed at the protein level." (PMID 25369402, 2014). "Here, we show that exogenous addition of recombinant TGFBI to BXPC3 tumor cells inhibited clonogenic growth and migration, thus recapitulating the phenotypic effect observed from DDR1 silencing." (PMID 25369402, 2014). "Others have shown that ectopic expression of TGFBI in transformed cells significantly suppresses tumorigenicity in multiple tumors, indicating that frequent downregulation of TGFBI is involved in tumor progression." (PMID 25369402, 2014). "On the contrary, the pro-tumorigenic action of CAFs can be reverted by exposure to certain tumor-inhibitory factors such as TGFBI, and tumor-resident fibroblasts can suppress tumor growth in a proper microenvironment." (PMID 24734219, 2014). "From both analyses, we identified TGFBI as one of the genes that was upregulated upon DDR1 knockdown in BXPC3 tumor cells." (PMID 25369402, 2014). "Together, these data suggest that DDR1 expression level influences tumor growth in part via modulation of TGFBI expression." (PMID 25369402, 2014).
tumor (continued). "TGFBI is ubiquitously expressed in adult normal tissues, although downregulation of this gene has been found in various human tumor cell lines and in primary tumor specimens." (PMID 25369402, 2014). "The TGFBI null mice, were reported to be prone to spontaneous tumor formation and showed more metastatic potential than TGFBI+/+ mice." (PMID 25369402, 2014). "Recombinant TGFBI was capable of inhibiting tumor cell growth in vitro as well as wound healing in a similar manner although there was no change in DDR1 expression." (PMID 25369402, 2014). "We demonstrated that silencing of DDR1 inhibited tumor cell growth and motility, and induced TGFBI expression, both in vitro and in vivo." (PMID 25369402, 2014). "Transforming growth factor β induced (TGFBI) product, an extracellular matrix (ECM) protein, has been implicated as a putative tumor suppressor in recent studies." (PMID 22695319, 2012). "In contrast, mice injected with TGFBI-expressing cells (T23108, T23109, and T23113) showed signs of tumor growth at 6 weeks post inoculation, 2 weeks later than control groups." (PMID 22695319, 2012). "The FAS1 domains of TGFBI have been shown to inhibit tumor angiogenesis and tumor growth and to promote apoptosis." (PMID 22695319, 2012). "It is worth noting that TGFBI, as an extracellular matrix protein, has been reported differently either as a tumor suppressor or over-expressed in tumors." (PMID 23077482, 2012). "In order to show the inhibitory effects of TGFBI on tumor growth at the molecular level, ki67, a molecular marker of cell proliferative capacity was used to stain the tissue slides dissected from tumors of each group." (PMID 22695319, 2012). "Transfection of TGFBI-expression plasmids into CHO cells led to a marked inhibition of tumor formation in nude mice." (PMID 22695319, 2012). "We also found that TGFBI protein localized not only in cell culture medium and cytoplasm, but also in the nuclei of TGFBI-transfected tumor cells and immortalized epithelial cells (Met-5A cells and MCF-10 F cells)." (PMID 22695319, 2012). "TGFBI has been suggested to have both tumor suppressor and tumor promoting properties, depending on the cancer of origin." (PMID 22640878, 2012). "Questions such as how TGFBI-derived peptides will affect non-tumor cells, which protease catalyzes TGFBI proteolysis and in what instances this proteolysis is activated all warrant future investigation." (PMID 20509890, 2010). "For cancer, reports highlight a tumor-suppressive role of TGFBI, and complementary expression patterns of periostin and TGFBI in the developing heart were explicitly studied." (PMID 20109226, 2010). "A set of proteins that correlate with the inhibition of tumor growth in the response to therapy included transforming growth factor-β induced (TGFBI), annexin A1 and protein disulfide-isomerase, which were increased." (PMID 21060779, 2010). "For TGFBI, we observed strong tumor specific immunoreactivities in most GBM samples with extra cellular staining pattern mainly in tumor cells and in malignant vasculature endothelial cells but negative staining in normal brain tissues." (PMID 20419098, 2010). "Methylation-specific primers were designed based on the methylation profiles of the TGFBI promoter in human tumor cell lines, and MSP conditions were optimized for accurate and efficient amplification." (PMID 18834524, 2008). "Hypermethylation of the TGFBI promoter has been shown to correlate with decreased expression of this gene in human tumor cell lines." (PMID 18834524, 2008). "We have shown previously that CpG islands of the TGFBI gene promoter are hypermethylated in human tumor cell lines." (PMID 18834524, 2008). "Future studies will be required to clarify the functional complexity of TGFBI in human tumor progression." (PMID 18834524, 2008).
tumor (continued). "In contrast, only sparsely methylated or unmethylated CpG sites were identified in cell lines with a rich level of TGFBI expression, including normal, immortalized, and several tumor cell lines." (PMID 18834524, 2008). "For this purpose, we designed three pairs of methylation-specific primers based on the methylation profiles of the TGFBI promoter reported in human tumor cell lines." (PMID 18834524, 2008). "Strikingly, multiparametric flow cytometry analyses revealed that TGFBI was abundantly expressed by tumor cells or monocytes, and by various lymphoid cell types-including CD4+ or CD8+ T cells (including tissue-resident memory T cells), B cells, and natural killer cells-in patients with cancer." (PMID 41927343, 2026). "Conversely, exosomes derived from tumor-associated macrophages led to increased expression of TGF-β signaling pathway activators in meningioma cells, specifically TGFBI, SNAI1, MMP2, TGF-β1, TGF-β2, IGFBP7, and LTBP2, leading to tumor cells obtaining a more aggressive phenotype." (PMID 40486962, 2025). "At the molecular level, TGFBI promotes tumor progression through multiple mechanisms." (PMID 40430059, 2025). "RUNX2 plays a critical role in tumor progression and bone metastasis, whereas TGFBI may contribute to immune evasion in the tumor immune microenvironment." (PMID 40963874, 2025). "Its hypoxia-dependent expression characteristics suggest that targeting TGFBI may be a potential strategy to enhance tumor treatment resistance, although its mechanisms in VaD require further investigation." (PMID 41377395, 2025). "To investigate the potential cooperation between OTUB1 and TGFBI in inhibiting tumor angiogenesis induced by curcumol, we employed immunofluorescence staining to assess the expression and co-localization of OTUB1 and TGFBI within the tumor tissues of nude mouse xenografts." (PMID 40430059, 2025). "In these models, TGFBI silencing reduced tumor growth and angiogenesis." (PMID 40082664, 2025). "Since apoptosis was a crucial mechanism through which cetuximab induced tumor cell death 30, MT1E and MT2A expression might correlate with enhanced drug sensitivity, while PCK1 and TGFBI expression might be linked to resistance." (PMID 40959565, 2025). "Our results indicated predominant TGFBI expression in tumor cells positive for HIF1α and CA9." (PMID 39346536, 2024). "Although TGFBI showed controversial functions in tumorigenesis, it was agreed that TGFBI could drive cancer progression by endowing tumor cells with highly metastatic capacity." (PMID 38395907, 2024). "IF analysis of mouse xenografts revealed that TGFBI inhibition decreased EphA2 levels in the tumor." (PMID 39346536, 2024). "Recent studies have also suggested that TGFBI may promote tumor growth and drug resistance by affecting the tumor microenvironment of pancreatic cancer." (PMID 39068456, 2024). "TGFBI may have a tumor suppressor or tumor promoter role depending on the stage of tumor progression." (PMID 38534368, 2024). "By searching SCP, we further verified that TGFBI mainly residents in malignant cell and putative tumor cells, it also showed that patients who received TKI treatment had lower TGFBI level, however, when comparing its profiles in ICB responders and ICB non responders, there was no notable difference." (PMID 39068456, 2024). "Bioinformatics analysis suggests that TGFBI may exert its influence on various biological processes in RCC through the tumor immune microenvironment." (PMID 39068456, 2024). "In addition, the double Cat D and TGFBI KO rescued the inhibitory effects of Cat D KO on tumor metastasis by controlling TAM and T-cell activation." (PMID 38297161, 2024). "Next, we investigated whether blocking TGFBI in Cat D KO tumors controls tumor metastasis in immunodeficient (SCID) mice." (PMID 38297161, 2024). "Moreover, TGFBI sustains tumor cell survival after radiotherapy via stimulating FAK pathway activation in gastric cancer." (PMID 36906534, 2023).
tumor (continued). "Indeed, this is not a surprising issue due to the previously reported modulating effect of DDR1 on TGFBI which often acts as a tumor promoter." (PMID 37271822, 2023). "The level of TGFBI has been suggested as a biomarker for tumor progression." (PMID 37835457, 2023). "Downregulation of DDR1 triggers TGFBI secretion and tumor progression." (PMID 36906534, 2023). "Furthermore, a highly expressed marker was TGFBI in the tumor core of immune cells, which was prolonged considered to be originating from malignant cells." (PMID 37434432, 2023). "Recent studies demonstrated that TGFBI also enhances hypoxia and glycolysis in cells in the tumour microenvironment and mediates the immune tolerance of CSCs, which could be crucial for CSC maintenance and metastasis." (PMID 34548635, 2022). "For instance, TGFBI can work as a tumor inhibitor or promoter in ovarian cancer." (PMID 35083181, 2022). "The expressions of IFI30 and TGFBI in tumor and normal tissues were verified by THPA database." (PMID 35634956, 2022). "The exact mechanism of TGFBI linking TAM functions to GSC-driven tumor growth was explored." (PMID 35673564, 2022). "In addition, our in vitro experiments also demonstrated that the ZEB2 expression of UM-Chor1 was significantly downregulated after the application of inhibitors, which targeted TGFBI, and the invasiveness of tumor cells was correspondingly attenuated." (PMID 36127333, 2022). "TGFBI+ M0‐like TAMs are a kind of blood‐derived monocyte‐derived TAMs gradually polarized to M2 under the influence of hypoxia‐influencing factors after entering tumor tissue." (PMID 35634956, 2022). "TGFBI has been reported to be both a tumour promoter and suppressor." (PMID 34548635, 2022). "Since both aberrantly expressed LIN28B and a high TGFBI tumour microenvironment are related to a more advanced disease stage among multiple tumour types, this interaction may also be important for LIN28B-positive CSC-like cells in other tissues." (PMID 34548635, 2022). "To determine whether TGFBI can mediate the tumor-promoting effect of M2-like TAMs, we studied the potential co-distribution between TGFBI and GSCs in human GBM frozen sections." (PMID 35673564, 2022). "However, a recent study found that Dkk-3 CRD1 interacts with the ECM protein, transforming the growth factor beta-induced (TGFBI), a secreted protein that has pro-invasive features and has been classified as a tumor-promoting factor." (PMID 36497305, 2022). "Yet, this knowledge is crucial to understand TGFBI role in the early phases of tumor progression." (PMID 33408771, 2021). "A study suggested TGFBI may play a pro-tumor or anti-tumor role, depending on the integrins to which it binds on the cell surface." (PMID 33912443, 2021). "Furthermore, we applied the Oncomine database to compare TGFBI expression between tumor and matched normal tissues." (PMID 34671645, 2021). "Many reports have indicated that TGFBI functioned as a tumor suppressor." (PMID 33912443, 2021). "Whether TGFBI produced by myCAFs and myofibroblasts is functionally different from that secreted by tumor cells awaits further investigation." (PMID 34869001, 2021). "Considering the role of TGFBI in tumor angiogenesis, adipocyte differentiation, and endothelial cells, we hypothesized that it may act as a regulator of angiogenic sprouting in adipose tissue." (PMID 33958649, 2021). "Patients with high tumor expression of TGFBI have significantly shorter OS." (PMID 33921897, 2021). "Multiple studies report a tumor-promoting function of TGFBI." (PMID 33912443, 2021). "Furthermore, we assessed the correlations between TGFBI expression and tumor stemness in a pan-cancer analysis using TCGA data." (PMID 34671645, 2021). "Interestingly, TGFBI exhibits dual functions in ovarian cancer (OV) by acting as both a tumor promoter and suppressor." (PMID 34671645, 2021).
tumor (continued). "The KEGG analysis showed that the “PI3K-Akt signaling pathway”, “Focal adhesion”, and “ECM–receptor interaction” might be involved in the effects of TGFBI on tumor pathogenesis." (PMID 34671645, 2021). "The differences observed between our study and previously published data might be due to methodological differences, in particular the fact that we focused on the role of TGFBI in the tumour microenvironment using a knockout mouse." (PMID 33080107, 2020). "Furthermore, FN1, TNC, and TGFBI have been reported to promote tumor migration, invasion, and adhesion, which are functions facilitating metastatic spread." (PMID 32312959, 2020). "In view of these results, we next aimed at understanding whether depletion of TGFBI impacts the tumour vasculature functionality." (PMID 33080107, 2020). "In accordance with these reports, we demonstrated that TAM secrete higher amounts of TGFBI compared to other cell populations in the ascites, e.g., tumor cells or TATs, and that TGFBI in the TAM secretome enhances tumor migration proven by neutralizing antibodies and RNA silencing." (PMID 32312959, 2020). "MSC-secreted EVs bearing TGF-β-induced gene product-h3 (TGFβI/BIGH3) could ameliorate osteoarthritis, however they can worsen tumor development by suppressing the activity of immune cells." (PMID 32326444, 2020). "Therefore, we investigated the role of TGFBI on tumor cell proliferation by siRNA mediated gene silencing of TGFBI." (PMID 31514337, 2019). "However, in other cancers, such as colon or pancreas, TGFBI has been described as having a tumor-promoting function." (PMID 31277676, 2019). "TGFBI is an extracellularly secreted matrix protein, proven to exist in normal and tumor cells." (PMID 31514337, 2019). "Besides, the xenograft animal study showed that TGFBI knockout suppressed tumor growth and metastasis in vivo." (PMID 31598162, 2019). "Several studies showed that TGFBI was abnormally overexpressed and could act as a tumor-promoting gene in gastric cancer, colon cancer, bladder cancer, and esophageal squamous cell carcinoma 12-15." (PMID 31598162, 2019). "Additionally, after administration of TGF-β1 (increasing TGFBI level), the volume of tumor is obviously reduced in nude mice with injection of L02 cells stable expressing truncated HBsAg." (PMID 29609638, 2018). "As in the case of therapeutic approaches that target TGF-β in cancers, TGFBI inhibition may stimulate or suppress tumor growth, although several reports indicate that TGFBI promotes the growth of gastrointestinal tumors." (PMID 28106769, 2017). "Like TGF-β, TGFBI acts as both a tumor suppressor and promoter in several types of cancer and may be a useful therapeutic target in gastrointestinal tumors." (PMID 28106769, 2017). "Based on the previous evidences, we speculated that TGFBI may be a tumor suppressor for NSCLC and may be responsible for the CAFs migration in NSCLC." (PMID 28231844, 2017). "This suggests that high levels of TGFBI in the stroma and not in tumor cells underlies tumor aggressiveness in ESCC." (PMID 28106769, 2017). "The comparison of FA with FTC tumours revealed that the 72 kDa extracellular protein TGFBI could correctly separate most FTC samples from the FA group with a relatively high fold change." (PMID 27025787, 2016). "Regardless, SPARC is likely a key component in organizing ECM proteins such as TGFBI in the tumor microenvironment and both may be prognostic indicators of chemotherapeutic response." (PMID 27622658, 2016). "Since SPARC is secreted into the extracellular tumor microenvironment and is required for TGFBI fibrillar deposition, its expression may indirectly influence chemotherapeutic response." (PMID 27622658, 2016). "Clinical and mechanistic results argue for TGFBI as both tumor suppressor and promoter." (PMID 25889002, 2015). "Further, the serum TGFBI levels are influenced by tumor treatment." (PMID 25889002, 2015).